CXCR4 (C-X-C motif chemokine receptor 4)
Diseases named in the same sentence as CXCR4 in open-access papers (continued):
Sharing a sentence is not in itself a finding about the gene and the disease.
leukemia (continued). "CXC chemokine receptor 4 (CXCR4), which is a prognostic marker for gastric cancer, leukemia, and other cancers, and can increase levels of its downstream molecule LCP1, is activated by the regulator GLI1." (PMID 31360146, 2019). "A little later, a similar model (i.e., leukemia-stromal cell interactions in OT) was used to determine the influence of SDF-1/CXCR4 signalling pathway on cell adhesion and migration." (PMID 31285461, 2019). "CXCR4 is expressed not only on the surface of hematopoietic stem cells, but also expressed on leukemic blasts and leukemia cell lines." (PMID 31518054, 2019). "Voerman et al17 confirmed that the migration ability of leukemia cells was positively correlated with the surface expression rate of CXCR4 and the chemotaxis of SDF‐l/CXCR4." (PMID 31518054, 2019). "Crazzolara et al28 also proved that the increased expression of CXCR4 in leukemia cells indicated the extramedullary organ infiltration of leukemia cells." (PMID 31518054, 2019). "To investigate this, we measured the expression of CXCR4 on leukemia cells at varying stages of disease." (PMID 30422351, 2019). "CXCR4 is critically involved in the cross-talk between leukemia cells and the bone marrow microenvironment and has been suggested as a worthwhile target to eradicate leukemia." (PMID 30841639, 2019). "Further, they establish CXCR4 as being a key candidate molecule to further study and manipulate in an effort to improve the ability of these populations to target leukemia and myeloma." (PMID 31231387, 2019). "The interaction between CXCR4 on leukemia progenitors and CXCL12 on BM stromal cells favors LSC homing to the BM microenvironment." (PMID 29466292, 2018). "LY2510924, a second generation CXCR4, showed significant anti-leukemia activity in a murine AML model." (PMID 30319961, 2018). "Overall, our data suggest that in Notch3-induced T-ALL leukemia, high Notch3 and CXCR4 co-expression marks “pre-leukemic” DP thymocytes and allows their egression and propagation outside the thymus." (PMID 30038265, 2018). "Previous experiments focused on the effects of uPAR 3’UTR on the expression of uPAR itself and of CXCR4, which is known to be co-regulated with uPAR by common miRs in leukemia cells." (PMID 29963240, 2018). "Based on these findings, CXCR4 antagonists not only having single agent activity but also enhance anti-leukemia effects of cytarabine and doxorubicin in AML." (PMID 30319961, 2018). "De novo, we propose that hyperactive Notch3 signaling by boosting CXCR4-dependent migration promotes anomalous egression of CD4+CD8+ cells from the thymus in early leukemia stages." (PMID 30038265, 2018). "AMD3100 is a clinically-approved CXCR4 antagonist used in combination with granulocyte-colony stimulating factor (G-CSF) to mobilize leukemia and lymphoma cells into the bloodstream where they become vulnerable to cytarabine and anthracycline chemotherapy." (PMID 29682200, 2018). "Interaction of SDF-1/CXCR4 was assayed in human leukemia CCRF-CEM cells expressing high levels of human CXCR4, MDA-MB-435 cells stably transfected with monkey CXCR4, and mouse 2PK-3 lymphoma cells expressing high levels of mouse CXCR4." (PMID 29212254, 2017). "We also tested the efficacy of PF-06747143 in leukemia growth in a PDX model reconstituted with P15 AML patient primary cells characterized by high CXCR4 expression (P15CXCR4-high)." (PMID 28779088, 2017). "Clinical trials investigating plerixafor and other agents targeting CXCR4, including anti-CXCR4 monoclonal antibodies and peptide CXCR4 antagonists, for leukemia and lymphoma are currently under way." (PMID 29299123, 2017). "The CXCL12-CXCR4 axis plays an important role in the leukemia-microenvironment since CXCR4 inhibitors mobilize leukemia cells from bone marrow into circulation, and increase chemo-sensitivity." (PMID 27481339, 2016). "Several forms of hematologic malignancies including leukemia and lymphoma are also shown to express high levels of CXCR4." (PMID 26954567, 2016).
leukemia (continued). "This suggests that activation of CXCR4 induced by CXCL12 occurs either by cell-cell interactions with non-leukemia CXCL12 expressing cells, likely located in lymphatic tissues, or mediated by soluble CXCL12." (PMID 26646452, 2016). "In mouse xenograft models developed with human leukemia and lymphoma cells expressing high levels of CXCR4, LY2624587 exhibited dose-dependent tumor growth inhibition and provided significant survival benefit in a disseminated lymphoma model." (PMID 26954567, 2016). "AMD3100 (plerixafor), the most commonly used drug to inhibit the receptor CXCR4, is currently in clinical trials for glioma, leukemia, Ewing sarcoma, neuroblastoma and brain tumors and is already FDA-approved for Non-Hodgkin's lymphomas and multiple myeloma." (PMID 26744352, 2016). "The bicyclam AMD3100, also known as plerixafor, is a CXCR4 antagonist and has been introduced in clinical trials to treat different tumor types, mainly leukemia and lymphomas." (PMID 26744352, 2016). "To simulate 2° TD events after migration, we used a murine leukemia cell line, L1210, which constitutively overexpresses the chemokine receptor CXCR4." (PMID 27865213, 2016). "In human lymphoma U937 and leukemia CCRF-CEM cells expressing endogenous CXCR4, LY2624587 inhibited SDF-1-induced cell migration with IC50 values of 3.7 and 0.26 nM, respectively." (PMID 26954567, 2016). "It is well established that interactions between the chemokine CXCL12, secreted by BM stromal cells, and its receptor CXCR4, expressed on the surface of leukemic cells, are very important for protecting leukemia cells from chemotherapeutic drugs." (PMID 27776559, 2016). "CXCR4/CXCL12-mediated leukemia/stromal interactions are known to contribute to chemoresistance in CML and are greatly diminished if CXCL12 concentration or activity is reduced." (PMID 26431162, 2015). "Overexpressed adhesion molecules, including CXCR4 and VLA-4 on leukemia cells are associated with a higher risk of relapse 5–7." (PMID 26139471, 2015). "A direct miR-mediated regulation of uPAR or CXCR4 expression in leukaemias has been scarcely investigated." (PMID 26082201, 2015). "Although various CXCR4 antagonists have the function of mobilizing leukemia cells from bone marrow, E5 has one distinguished advantage over others-good safety." (PMID 26538086, 2015). "In a case study, the role of stroma-secreted chemokine stromal-derived factor 1 (SDF-1) and its cognate receptor CXCR4 in leukemia/bone marrow cell interaction were particularly investigated." (PMID 26652601, 2015). "Disruption of these interactions by SDF-1/CXCR4 antagonists represents a novel strategy for targeting leukemia/bone marrow microenvironment interactions." (PMID 26652601, 2015). "CXCR4- and integrin-mediated contact between leukaemia cells and stromal cells protects them from spontaneous and chemotherapy-induced cell death 23,24." (PMID 26082201, 2015). "We identified three miRs targeting both uPAR and CXCR4; identified miRs were validated and their expression and functions were examined in leukaemia cell lines and in blasts from AML patients." (PMID 26082201, 2015). "It has been reported that the SDF-1 chemokine, which binds to CXCR4, regulates the trafficking of CXCR4+ leukemia cells." (PMID 26652601, 2015). "CXCR4 plays a key role in tumor cell dissemination and metastasis development in the majority of cancers and several types of leukemia." (PMID 25866764, 2015). "For example, to study the interaction between leukemia cells and stromal cells in bone marrow microenvironment, SDF-1/CXCR4 were found to connect the stromal cell and leukemia cell and involved in cancer therapy." (PMID 26652601, 2015). "In leukemia, CXCR4 expression conferred leukemic blasts with a higher capacity to seed into BM niches, thereby protecting leukemic cells from chemotherapy-induced apoptosis, and was correlated with shorter disease-free survival." (PMID 25704881, 2015).
leukemia (continued). "Collectively, CXCR4 antagonists offer a new tool to mobilize leukemia cells from their protective bone marrow niche." (PMID 27429863, 2015). "Previous studies reported that treating leukemia with a combination of CXCR4 inhibitors and chemotherapeutic agents produced additive therapeutic effects." (PMID 25544759, 2015). "In vitro and in vivo evidence suggest that CXCR4 expression by leukaemia cells allows for their homing and retention within the BM, accessing niches that are normally restricted to progenitor cells." (PMID 26082201, 2015). "We then evaluated the expression of selected miRs and of their identified targets, uPAR and CXCR4, in leukaemia cell lines." (PMID 26082201, 2015). "As reported in the literatures, SDF-1 and CXCR4 regulate the adhesion, homing, and mobilization of leukemia cells." (PMID 26652601, 2015). "The CXCR4 antagonist AMD3100 mobilized leukemia cells into the peripheral circulation and sensitized these cells to the in vivo effects of cytotoxic chemotherapy." (PMID 26139471, 2015). "In this paper, the role of SDF-1/CXCR4 signaling pathway to the interaction between leukemia cells and bone marrow cells at single cell level was studied using the proposed cell adhesion manipulation tool." (PMID 26652601, 2015). "Conversely, neutralizing the interactions of CXCL12/CXCR4 disrupted metastasis, induced apoptosis, and increased chemosensitivity in solid cancers and leukemia." (PMID 25704881, 2015). "In conjunction with its CXCL12 ligand, CXCR4 mediates leukemia cell trafficking and homing to the bone marrow microenvironment in close proximity to marrow stromal cells." (PMID 27429863, 2015). "Since both uPAR and CXCR4 are up-regulated in leukaemias, we focused on miRs endowed with oncosuppressor activity and involved in CD34+ HSCs mobilization and/or expressed in leukaemias." (PMID 26082201, 2015). "Specifically, CXCR4 expression was highest in leukemia cells circulating in the peripheral blood and lowest in those localized to the bone marrow, while CD49d expression was highest in the bone marrow and lowest in the peripheral blood." (PMID 25333254, 2014). "Most findings on the effects of CXCR4 antagonists in human cancer were obtained in hematological malignancies, disrupting the interactions between CXCR4-expressing leukemia cells and CK secreted by the bone marrow microenvironment." (PMID 24904289, 2014). "Among current developed CXCR4 antagonists, peptides are one attractive class to inhibit leukemia cells migration, invasion and adhesion, and to interfere with stromal cell-mediated tumor cell drug-resistance." (PMID 25312253, 2014). "Recent preclinical studies in mouse models of leukemia have provided proof of concept for the greater benefits of combining CXCR4 inhibition with conventional chemotherapy relative to chemotherapy treatment alone." (PMID 24475985, 2014). "Previous studies have suggested an interaction between hyaluronan-activated CD44 and CXCL12/CXCR4 signaling in induction of leukemia cell and human umbilical endothelial cell-polarization and subsequent migration." (PMID 24614402, 2014). "The CXCR4 gene is a chemokine receptor and has recently attracted attention as a prognostic factor for disease relapse and survival in leukemia patients." (PMID 24613624, 2014). "Additional constituents of BM niche, the stroma-secreted chemokine CXCL12 and its receptor CXCR4 play crucial roles in cell migration and stroma/leukemia cell interactions." (PMID 23826077, 2013). "In chronic myeloid leukemia, BMSCs stabilize leukemia cells by promoting the clustering of CXCR4 in the lipid rafts and facilitating the migration of leukemia cells in the bone marrow." (PMID 24304929, 2013). "Leukemia and lymphoma B cells express functional chemokine receptors including CXCR4 and are capable of directional migration (chemotaxis) by following gradients of chemokines such as SDF-1 (CXCL12), the ligand of CXCR4." (PMID 23460911, 2013).
leukemia (continued). "A receptor antagonist Plerixafor is known to block active CXCL12/CXCR4 signaling in normal and leukemia stem cell." (PMID 23826077, 2013). "We further investigated the antileukemic efficacy of 1D11 combined with CXCR4 antagonist Plerixafor in an in vivo leukemia model." (PMID 23826077, 2013). "Treatment with 1D11 combined with CXCR4 antagonist plerixafor and Ara-C decreased leukemia burden and prolonged survival in an in vivo leukemia model." (PMID 23826077, 2013). "The role of CXCR4 in leukemia retention was illustrated by experiments that demonstrated reduction of primary human AML cell numbers previously engrafted in immunodeficient NODscid mice with antibody to CXCR-4." (PMID 22346731, 2012). "Leukemia cell mobilization from the bone marrow into peripheral blood in vivo using a CXCR4 inhibitor induced chemo-sensitization of leukemia cells to cytarabine, which translated into a prolonged survival advantage in our mouse leukemia model." (PMID 22629369, 2012). "These latter two studies demonstrated the proof of principle that the concept that a combination of a CXCR4 inhibitor with chemotherapy or targeted therapy was efficacious in enhancing leukemia cytotoxicity in vivo." (PMID 22346731, 2012). "A recent study showed that a CXCR4 antagonist, plerixafor, increased the sensitivity of leukemia cells to chemotherapy." (PMID 23226219, 2012). "We previously published that M2-BMSCs protect leukemic blasts from cytotoxic agents, such as Ara-C, in vitro and that disruption of the BM microenvironment in vivo with the CXCR4 antagonist AMD3100 sensitizes leukemia cells to chemotherapy." (PMID 22629369, 2012). "It was shown that in leukemia cells, several growth and survival factors from the tumor microenvironment, including CXCR4 activation, induce PI3K activation." (PMID 20049170, 2010). "Stromal cells within bone marrow microenvironment constitutively secrete CXCL12 and the activation of CXCR4 induces leukemia cell migration to the marrow microenvironment, providing growth and drug resistance signals." (PMID 20049170, 2010). "Hence, upon targeting CXCL12-CXCR4 axis by a CXCR4 antagonist – Plerixafor, disrupt homing of leukaemia stem cell (LSC) to the bone marrow niche." (PMID 40852716, 2025). "A high expression of the CXC chemokine ligand 4 (CXCR4) and the activation of the CXCR4-CXCL12 axis may be associated with homing to the extramedullary niche where the leukemia cells proliferate." (PMID 41463221, 2025). "Enhances the specific apoptotic effects of KLA peptides in CXCR4-positive leukemia cells." (PMID 40496863, 2025). "A study utilized AMD3100 (also known as Plerixafor, which is clinically used in the treatment of leukemia for stabilizing hematopoietic stem cells) as an antagonist of CXCR4 against CAF-derived CXCL12/CXCR4 mediated signaling that facilitates invasion of cancer cells." (PMID 38562556, 2024). "targeting CXCL12/CXCR4 have been developed for leukemia treatment, it is essential to recognize that any aberrations (such as intrinsic genetic variations or external factors disrupting homeostasis) may contribute to leukemia initiation." (PMID 38920657, 2024). "This suggests that Nrf2 overexpression in MSCs when co-cultured with leukemia cells promotes leukemia cell infiltration in extramedullary organs by activating the phosphorylation of the SDF-1/CXCR4 signaling axis and its downstream pathway, shortening the survival time of mice." (PMID 39081954, 2024). "This also shows that overexpression of Nrf2 in MSCs could promote the phosphorylation of the downstream pathways through activation of the SDF-1/CXCR4 axis, which led to a series of cascade reactions and promoted the migration and invasion of leukemia cells." (PMID 39081954, 2024). "While our study focused on elderly AML patients, the prognostic significance of SDF1/CXCR4 in pediatric AML may differ due to the distinct biological characteristics of childhood leukemia." (PMID 39871937, 2024).
leukemia (continued). "Similarly, Levy and colleagues successfully transfected NK cells in vitro with CXCR4 mRNA via electroporation, suggesting that CXCR4 overexpression is a promising approach to tackle tumors in the bone marrow, such as myeloma and leukemia." (PMID 39339180, 2024). "Suggesting that the activated SDF-1/CXCR4 axis might further activate the ERK signaling pathway to promote leukemia cell proliferation." (PMID 37670388, 2023). "As implied by these findings, the pro-proliferative function of IFI6 for leukemia cells might be exerted through the SDF-1/CXCR4/ERK signal stimulation." (PMID 37670388, 2023). "We speculated whether the increased expression of IFI6 in MSCs could facilitate the leukemia cell multiplication by stimulating the SDF-1/CXCR4 axis." (PMID 37670388, 2023). "The fact that CXCR4 expression levels in B-ALL cells inversely correlate with patient outcome suggests that B-ALL-induced changes in the BM microenvironment may favor leukemia progression." (PMID 36912771, 2023). "The CXCR4/SDF-1 axis may contribute to chemoresistance through downstream signaling cascade dysregulation within leukemia cells." (PMID 36900239, 2023). "Mechanistically, IFI6 might promote leukemia cell proliferation by stimulating SDF-1/CXCR4 axis, which leads to the initiation of downstream ERK signaling pathway." (PMID 37670388, 2023). "In addition, both anaesthetics sensitised leukaemia cells to Ara-C possibly through CXCR4 mediated mechanisms." (PMID 38798305, 2022). "CXCR4 inhibitors, such as plerixafor, BL-8040, and LY2510924, could disrupt the chemotaxis mediated by the CXCL12/CXCR4 axis and dislodge the leukemic cells from their protective BM niches to increase the sensitivity of leukemia cells to chemotherapy." (PMID 36163119, 2022). "Taken together, these results indicate that T140-KLA-EVs are safe and effective in treating leukemia in vivo by potentiating the apoptotic effects of the KLA peptide specifically in CXCR4-positive leukemia cells, thereby slowing the progression of the disease and improving the overall survival." (PMID 35547755, 2022). "Other novel CXCR4 inhibitors have also exhibited significant anti-leukemia activities in T-ALL." (PMID 36428753, 2022). "CXCR4 antagonists may mobilize drug‐resistant leukaemia cells or leukaemia‐initiating cells, chemotherapy or molecular target drugs may not kill them effectively, and new combinational strategies still need to be explored." (PMID 34050566, 2021). "CXCR4‐targeted endoradiotherapy efficiently reduced leukaemia cells in the T‐ALL PDX model." (PMID 34050566, 2021). "The results revealed that compared with the leukemia cells in the control group and EV group, up-regulating CXCR4 in leukemia cells obviously enhanced the promotion effect of TGF-β conditioned MSCs on the migration and invasion of Nalm-6/RS4;11 cells (P < 0.05)." (PMID 34733839, 2021). "We next examined the potential of CXCR4 as a therapeutic target in CALM-AF10-driven leukemia." (PMID 35070954, 2021). "Ultimately, CXCR4 expression on leukemic blasts varies, and the factors influencing differences in expression, function, and downstream signaling in leukemia are unknown." (PMID 35070954, 2021). "Additional studies are needed to establish whether CXCR4 inhibition impacts other characteristics of CALM-AF10 leukemia, including CNS invasion." (PMID 35070954, 2021). "Thus, when used alone or in combinational therapies, CXCR4 antagonists were found to significantly inhibit the growth of leukaemia cells and prolong the survival of leukaemic mice." (PMID 34050566, 2021). "Furthermore, the authors showed that targeting CXCR4 both in mice and in human xenograft models suppressed leukemia progression." (PMID 33374160, 2020).